RNU6-679P (RNA, U6 small nuclear 679, pseudogene)
Gene: Small nuclear RNA gene on chromosome 5 (12,297,399 to 12,297,504, reverse strand). Ensembl gene ENSG00000212305.
Homologues: Orthologues: chimpanzee U6 (98% identical), macaque U6 (96% identical), dog U6 (78% identical), rabbit U6 (77% identical), guinea pig U6 (74% identical), dog U6 (71% identical). Paralogues in human: RNU6-1124P (83% identical), RNU6-140P (82% identical), RNU6-147P (82% identical), RNU6-16P (82% identical), RNU6-19P (82% identical), RNU6-338P (82% identical), RNU6-536P (82% identical), RNU6-820P (82% identical), RNU6-854P (82% identical), RNU6-1040P (81% identical), RNU6-1099P (81% identical), RNU6-29P (81% identical), and 1285 more.